LARP1 (La ribonucleoprotein 1, translational regulator)
Diseases named in the same sentence as LARP1 in open-access papers (continued):
Sharing a sentence is not in itself a finding about the gene and the disease.
cervical cancer (10 papers, 2015 to 2024). A primary or metastatic malignant neoplasm involving the cervix. "In HeLa (cervical cancer) cell lines, loss of LARP1 by transient RNAi, stable transfection or lentiviral knockdown causes a proportion of them to undergo apoptosis." (PMID 26501340, 2015). "Likewise, the expression of LARP1 was upregulated in cervical cancer and NSCLC, and its expression was associated with disease progression and adverse prognosis." (PMID 32953888, 2020). "Increased levels of LARP1 in cervical cancer facilitate the migration and invasion of cancer cells by acting on mRNAs rich in carcinogenic transcripts." (PMID 38283117, 2024). "Levels of LARP1 protein correlate with increasing disease progression in cervical cancer where there are stepwise elevations in LARP1 expression through the pre-invasive stages (CIN1-3) and into invasive disease." (PMID 26501340, 2015). "In non-small cell lung and cervical cancer, higher levels of LARP1 protein correlate with tumor progression and adverse survival." (PMID 25531318, 2015). "Although LARP1 plays an important role in tumorigenesis and progression of cervical cancer, non-small cell lung cancer, HCC, and prostate cancer, the biological function and prognostic value of LARP1 expression in human colon cancer are still unknown." (PMID 27614686, 2016). "LARP1 not only participates in embryogenesis, mitotic spindle pole formation, successful mitochondrial isolation, and cell cycle progression, but also acts as a viral host factor and is upregulated in various tumor tissues, such as cervical cancer and liver cancer." (PMID 37206976, 2023). "In addition, LARP1 can positively regulate the mRNA expression of multiple components of the mTOR carcinogenic pathway and other anti-apoptotic [B-cell lymphoma 2 (BCL2)] and pro-migration [Y-box binding protein-1 (YB1)] proteins, leading to LARP1-mediated cervical cancer tumorigenesis." (PMID 37507746, 2023). "Knockdown of LARP1 in OVCAR3 and IGROV-1 lines, and in cervical cancer-derived HeLa cells, resulted in a significant decrease in CD133+ cell populations." (PMID 26717985, 2016). "We found significant increased levels of LARP1 in cervical intraepithelial neoplasia versus normal epithelium and cervical SCC versus cervical intraepithelial neoplasia, confirming that cytoplasmic LARP1 significantly correlated with progression of cervical cancer." (PMID 25531318, 2015).
colorectal cancer (10 papers, 2016 to 2025). A primary or metastatic malignant neoplasm that affects the colon or rectum. "Hsa_circRNA_002144 promotes colorectal cancer growth and metastasis through the miR-615-5p/LARP1/mTOR pathway." (PMID 40018039, 2025). "Specifically, in colorectal cancer, LARP1 has been confirmed as the RNA‐binding protein with the strongest upregulation, playing a role in fostering tumor expansion." (PMID 39786317, 2025). "The LARP1/mTOR axis has been shown to facilitate the proliferation and metastatic spread of epithelial and colorectal cancers." (PMID 39786317, 2025). "LARP1 plays an important role in the proliferation of colorectal cancer and represents a new prognostic indicator." (PMID 27614686, 2016). "The gene expression of LARP1 at the mRNA level was evaluated by the real-time PCR analysis of 40 pairs of colorectal cancer tissues and their paired adjacent normal mucosa." (PMID 27614686, 2016). "Interestingly, a feedforward loop between MYC and LARP1 was recently identified to promote tumorigenesis in colorectal cancer." (PMID 38067212, 2023). "At the same time, LARP1 can be used as a prognostic marker of colorectal cancer (CRC)." (PMID 36335189, 2022). "Additional studies are needed to investigate whether LARP1 mediated cellular proliferation and prognosis of colorectal cancer by interacting with mTOR." (PMID 27614686, 2016). "The results demonstrated that LARP1 was a potential biomarker of colorectal cancer." (PMID 27614686, 2016). "However, the role of LARP1 in the prognosis and cellular proliferation of colorectal cancer has yet to be defined." (PMID 27614686, 2016). "This study investigated the significance of La-related protein 1 (LARP1) in the development and progression of colorectal cancer (CRC)." (PMID 27614686, 2016). "Using laser capture microdissection, we obtained purified cell populations from heterogeneous tissues and found that La-related protein 1 (LARP1), an RNA-binding protein (RBP), was overexpressed in colorectal cancer tissues compared with paired normal specimens." (PMID 27614686, 2016).
prostate carcinoma (9 papers, 2015 to 2022). A carcinoma that arises from epithelial cells of the prostate gland. "LARP1 is oncogenic with higher tumour levels of LARP1 protein corresponding with adverse prognosis in ovarian, colorectal and prostate cancer." (PMID 32286153, 2021). "In prostate cancer cells, tumour migration is attenuated upon LARP1 knockdown and LARP1 expression is negatively regulated by microRNAs mi-26a or b." (PMID 26501340, 2015). "Finally, as previously demonstrated in other cancer cell lines, the ablation of LARP1 largely blocked cell proliferation in multiple cancer cell lines including prostate cancer cells." (PMID 28650797, 2017). "Furthermore, there was an especially clear trend of higher LARP1 and RP protein expression in multiple prostate cancer cell lines (LnCap, 22RV1, PC3, and Du145) compared with those in non-transformed (PrEC) or transformed (PTN2 and RWPE) normal prostate epithelial cells." (PMID 28650797, 2017). "Again, there was clear positive correlation between the expression of LARP1 and the RP proteins (e.g. RpS6) but not between LARP1 protein and RpS6 mRNA in prostate cancer and normal cells." (PMID 28650797, 2017). "However, in response to growth factor/amino acids stimulation, LARP1 knockdown significantly delayed and attenuated phosphorylation of these proteins in HEK293T cells, LnCap (prostate cancer cell line), and HEK293E cells (insulin sensitive)." (PMID 28650797, 2017).
hepatocellular carcinoma (7 papers, 2013 to 2023). A malignant tumor that arises from hepatocytes. "The diseases associated with LARP1 are dengue virus and hepatocellular carcinoma." (PMID 36979474, 2023). "The Kaplan–Meier survival curve showed that the patients with hepatocellular carcinoma in the high-risk group and those with NSUN2, NUDT3 and LARP1 genes in the high expression group had a lower survival rate and shorter survival time." (PMID 36335189, 2022). "As a promising biomarker, the expression of LARP1 is closely related to poor prognosis of early-stage and alpha-fetoprotein-normal hepatocellular carcinoma (HCC) patients." (PMID 27614686, 2016). "The aim of this study was to investigate the prognostic value of LARP1 in hepatocellular carcinoma (HCC)." (PMID 24159927, 2013). "In hepatocellular cancer (HCC), high levels of LARP1 protein in tumour tissue correlate with approximately 35% increased risk of death by five years (compared to low levels) and with tumour size, survival time and Child-Pugh score." (PMID 26501340, 2015).
breast carcinoma (6 papers, 2015 to 2023). "In conclusion, we identified a novel autophagy-related prognostic risk model consisting of six encoding gene (VPS35, TRIM21, PRKAB2, RUFY4, MAP1LC3A and LARP1) in breast cancer." (PMID 34001111, 2021). "In this study, the prognostic risk model consisting of six ARGs (VPS35, TRIM21, PRKAB2, RUFY4, MAP1LC3A and LARP1) in breast cancer were identified." (PMID 34001111, 2021). "In breast cancer, RNA-sequencing and high throughput software analyses of tissue samples revealed the presence of a novel LARP1 splice variation in 4/6 non-triple negative cases." (PMID 26501340, 2015). "LARP1 and AK3 are associated with OS in luminal A and luminal B breast cancers." (PMID 31308365, 2019). "Although no clinically significant LARP1 mutations have yet been identified in cancers, a LARP1 splice variant has been observed in breast cancer." (PMID 26501340, 2015). "Additionally, levels of LARP1 have also been noted to be high in non-virally associated cancers such as prostate and breast cancer." (PMID 26501340, 2015). "Having demonstrated that LARP1 targets CSC-like cells, we compared its effects to a positive control, salinomycin, identified as a selective inhibitor of breast cancer stem cell-like populations." (PMID 26717985, 2016).
liver cancer (6 papers, 2013 to 2025). An epithelial or non-epithelial malignant neoplasm that arises from the liver. "As LARP1 has been implicated in cervical, breast, and liver cancers through its interaction with cancer-sustaining mRNAs, the DM15 repeat is a potential cancer drug target." (PMID 26206669, 2015). "Similarly, mutations in LARP1, especially at the LARP1-T449 phosphorylation site, have been shown to play an important role in liver cancer." (PMID 40018039, 2025). "Research indicates that LARP1 is associated with the infiltration of various immune cells and may facilitate the conversion of “cold” tumors to “hot” tumors in liver cancer." (PMID 40018039, 2025). "Levels of LARP1 are upregulated in breast, cervical, and liver cancers and the protein is tumorigenic." (PMID 26206669, 2015). "Among the genes associated with the prognosis of liver cancer, the genes associated with shorter survival period are AGO2, DCPS, IFIT5, LARP1, NCBP2, NUDT10, and NUDT16; the genes associated with longevity are EIF4E3, EIF4G3, METTL1, NCBP1, NSUN2, NUDT11, NUDT4, and WDR4." (PMID 36845384, 2023).
non-small cell lung carcinoma (5 papers, 2015 to 2022). A group of at least three distinct histological types of lung cancer, including non-small cell squamous cell carcinoma, adenocarcinoma, and large cell carcinoma. "Recently, LARP1 was shown to be overexpressed in cervical and non-small cell lung cancers, with increased expression correlated with cancer progression and poor prognosis." (PMID 27614686, 2016). "It has been demonstrated that LARP1 expression correlates with poor prognosis of non-small cell lung cancer and promotes cellular proliferation by interacting with mTOR." (PMID 27614686, 2016). "We demonstrate that LARP1 expression correlates with clinical outcome in cervical and non-small cell lung cancers and, at functional level, regulates cell migration, invasion, anchorage-independent and in vivo tumor growth." (PMID 25531318, 2015). "Furthermore, we show that LARP1 expression is elevated in epithelial cancers such as cervical and non-small cell lung cancers, where its expression correlates with disease progression and adverse prognosis, respectively." (PMID 25531318, 2015).
viral infection (4 papers, 2015 to 2025). "To further confirm that the cleavage observed under overexpression of 3Cpro also occurs during EV-D68 infection, we performed cleavage assays with wild-type LARP1 and its cleavage site mutants Q371A and Q790A in the context of viral infection." (PMID 40294010, 2025). "Although LARP1’s role in translation regulation is well-documented, its involvement in viral infections is not fully understood." (PMID 40294010, 2025). "Puromycin labeling revealed a marked decrease in mRNA translation upon PABPC1 or LARP1 knockdown, mirroring the effects of viral infection." (PMID 40294010, 2025). "We observed that viral infection inhibits these pathways, thereby impacting LARP1’s ability to regulate translation." (PMID 40294010, 2025). "Viral infection inhibits mTOR and CDK1 phosphorylation, which enhances LARP1’s binding to viral RNA and inhibits viral translation." (PMID 40294010, 2025). "With some evidence that LARP1 is a viral host factor, upregulation of LARP1 in these tumours could perhaps reflect ongoing viral infection rather than an active role in the cancer process." (PMID 26501340, 2015).
osteosarcoma (3 papers, 2020 to 2025). A usually aggressive malignant bone-forming mesenchymal neoplasm, predominantly affecting adolescents and young adults. "The downregulation of KCNQ1OT1 inhibits proliferation, invasion, and drug resistance in osteosarcoma cells through miR-129-5p-mediated LARP1 regulation." (PMID 40018039, 2025). "Further studies have found that LARP1 is a direct target of miR-129-5p and promotes the proliferation, invasion, and drug resistance of osteosarcoma cells." (PMID 32953888, 2020). "And the mRNA expression of LARP1 in osteosarcoma cell lines was significantly increased than normal osteoblast cell lines." (PMID 32953888, 2020). "Collectively, it suggests that downregulation of KCNQ1OT1 inhibits proliferation, invasion, and drug resistance by regulating miR-129-5p-mediated LARP1 in osteosarcoma cells." (PMID 32953888, 2020). "In addition, LARP1, as the target gene of miR-129-5p, promoted the proliferation, invasion, and drug resistance of osteosarcoma cells." (PMID 32953888, 2020). "Therefore, the knockdown of KCNQ1OT1 inhibits the occurrence and development of osteosarcoma via regulating the miR-129-5p/LARP1 axis." (PMID 32953888, 2020). "Likewise, in our study, LARP1, as a downstream target gene of miR-129-5p, promotes the proliferation, invasion, and drug resistance of osteosarcoma cells, which is consistent with previous studies." (PMID 32953888, 2020). "Therefore, the downregulation of KCNQ1OT1 inhibited proliferation, invasion, and drug resistance by regulating miR-129-5p-mediated LARP1 in osteosarcoma." (PMID 32953888, 2020). "In addition, miR-129-5p binds to LARP1 directly, and LARP1 promoted the proliferation, invasion, and drug resistance of osteosarcoma cells." (PMID 32953888, 2020). "In summary, our current study reveals that the knockdown of KCNQ1OT1 inhibits the occurrence and development of osteosarcoma by regulating the miR-129-5p/LARP1 axis, which suggests that KCNQ1OT1 might be a new biomarker related to proliferation and drug resistance of osteosarcoma." (PMID 32953888, 2020).
Clear Cell Renal Cell Carcinoma (2 papers, 2020 to 2025). "miR‐185‐5p/miR‐214‐3p are known to inhibit tumor growth and metastasis in clear cell renal cell carcinoma by targeting lncRNA ASB16‐AS1 and suppressing LARP1 expression." (PMID 39786317, 2025).
colon cancer (2 papers, 2016 to 2018). "A conspicuous expression of LARP1 was apparent in 61 (52.1 %) of 117 colon cancer tissue specimens." (PMID 27614686, 2016).
COVID-19 (2 papers, 2021 to 2022). A disease caused by infection with severe acute respiratory syndrome coronavirus 2. "Upstream regulator analysis identified five key regulators after exposure to COVID-19 in our study, one phosphatase (PDCD1), 3 transcriptional regulators (E2F3, NUPR1 and LARP1) and one mitotic spindle protein (CKAP2L)." (PMID 35547542, 2022).
gastric cancer (2 papers, 2024). A primary or metastatic malignant neoplasm involving the stomach. "The expression level of LARP1 was significantly higher in stomach cancer samples than in normal samples (P = 5.6 × 10−20)." (PMID 38283117, 2024). "This study aimed to clarify the role of la-related protein 1 (LARP1) in cell cycle progression and metastatic behavior of cultured gastric carcinoma (GC) cells." (PMID 38283117, 2024).
hepatoblastoma (2 papers, 2023 to 2025). Hepatoblastoma (HB) is a malignant hepatic tumor and is the most common pediatric liver cancer. "However, the expression pattern and biological role of LARP1 in hepatoblastoma (HB) remain unclear so far." (PMID 37070251, 2023).
melanoma (2 papers, 2021 to 2022). A malignant, usually aggressive tumor composed of atypical, neoplastic melanocytes. "The current research describes for the first time that the risk scores created by EIF4E3, LARP1, NCBP3, and IFIT5 can serve as independent prognostic factors for melanoma." (PMID 36473947, 2022). "To understand the role of m7GMRRGs in melanoma prognosis in further detail, we selected four m7GMRRGs (EIF4E3, LARP1, NCBP3, and IFIT5) to develop prognosis prediction model." (PMID 36473947, 2022).
multiple myeloma (2 papers, 2023 to 2025). "Additionally, we found expression of MYC, 4EBP1, LARP1, and hnRNPC to be significantly increased in primary samples from newly diagnosed multiple myeloma (NDMM) patients compared to plasma cells (PC) from healthy donors." (PMID 38067212, 2023).
Anxiety (1 paper, 2025). Intense feelings of nervousness, tension, or panic often arise in response to interpersonal stresses. "Mouse models of mTORC1 hyper-activation, where Larp1 is expected to be repressed, have complex behavioral phenotypes, including altered anxiety, autism-like behaviors and impaired cognitive function." (PMID 41278816, 2025).
atherosclerosis (1 paper, 2022). A disease characterized by the build-up of fatty material and calcium deposition in the arterial wall resulting in partial or complete occlusion of the arterial lumen. "In contrast, TNF, interferon regulatory factor 2 (IRF2) and interferon gamma (IFNG) were predicted to be inhibited and insulin activated in both datasets, and the computing of LARP1 activity was not possible in VAT samples from humans with atherosclerosis." (PMID 35737302, 2022).
B-cell non-Hodgkin lymphoma (1 paper, 2025). The most common type of non-Hodgkin lymphoma. "A LARP1::MRPL22 fusion has been reported to be recurrently expressed in B-cell non-Hodgkin lymphoma; however, its clinical significance remains unclear." (PMID 41373823, 2025).
cervical intraepithelial neoplasia (1 paper, 2015). "Using immunohistochemistry, we quantified LARP1 expression in a tissue microarray comprising tissue cores (n=83) from normal cervical epithelium, cervical intraepithelial neoplasia and invasive cervical SCC." (PMID 25531318, 2015).
colorectal tumor (1 paper, 2016). "LARP1 showed various expression levels in colorectal tumor tissues, including weak, moderate, and strong." (PMID 27614686, 2016).
diabetes (1 paper, 2021). "In summary, LARP1 is highly expressed in human β-cells and mouse islets, and is upregulated in diabetes." (PMID 33483593, 2021). "This is suggestive that LARP1 could be required for the high metabolic demand during the development of diabetes because LARP1 regulates proliferation and protein translation." (PMID 33483593, 2021). "Interestingly, diabetes increases LARP1 and LARP1B in human β-cells." (PMID 33483593, 2021). "The fact that mTORC1 and LARP1 interact to each other to control cellular protein translation capacity, and, more importantly, that mTORC1 activity and LARP1 expression are both increased in diabetes prompted us to generate a conditional mouse strain to disrupt LARP1 specifically in β-cells." (PMID 33483593, 2021). "However, the upregulation of LARP1B in diabetes might attenuate the absence of LARP1 in the responses to HFD or BCAA diet." (PMID 33483593, 2021).
epilepsy (1 paper, 2025). A brain disorder characterized by episodes of abnormally increased neuronal discharge resulting in transient episodes of sensory or motor neurological dysfunction, or psychic dysfunction. "Gene expression analysis of datasets GSE143272 and GSE190452 identified 8 differentially expressed m7G regulators (NUDT3, EIF4E3, LARP1, IFIT5, SNUPN, METTL1, EIF4A1, and LSM1) in epilepsy." (PMID 40658715, 2025). "The boxplot revealed that epilepsy patients had up-regulated expression levels of NUDT3, EIF4E3, LARP1, IFIT5, and SNUPN, and down-regulated expression levels of METTL1, EIF4A1, and LSM1." (PMID 40658715, 2025).
glioblastoma multiforme (1 paper, 2016). "Interestingly, LARP1 was one of the most strongly downregulated genes in non-CSC-like CD133− populations in a study investigating global differences in gene expression between CD133+ and CD133− cells derived from a patient with progressive glioblastoma multiforme." (PMID 26717985, 2016).
liver cirrhosis (1 paper, 2013). "But the LARP1 expression of liver cirrhosis patients did not change." (PMID 24159927, 2013).